INS (insulin)
Diseases named in the same sentence as INS in open-access papers (continued):
Sharing a sentence is not in itself a finding about the gene and the disease.
diabetes (continued). "In addition, it sought to examine secondary associations between AL and demographic or clinical variables, including sex, diabetes duration, insulin use, and presence of diabetic macular edema." (PMID 41356947, 2025). "Iterative advancements in diabetes technology including lower basal glucose targets and several active insulin time settings that personalize AID have been integral to improved HbA1c and CGM-derived glucose metrics, physiological normalization, and better psychosocial outcomes." (PMID 41488135, 2025). "Also, biovariance is particularly relevant in metabolic disorders like diabetes, where individual differences in insulin sensitivity, glucose metabolism, and mitochondrial function can significantly alter drug responses." (PMID 40004246, 2025). "For those with diabetes, this might look like managing persistent hyperglycemia by ‘rage bolusing’ or avoiding diabetes distress by forgoing or delaying checking blood glucose, dosing insulin, fulfilling prescriptions, and making dietary changes." (PMID 40564574, 2025). "However, it has been reported that in rats with streptozotocin-induced diabetes, Timbe (pods) significantly reduced blood glucose levels, increased serum insulin concentrations, decreased lipid levels, and improved indicators of kidney damage." (PMID 40284028, 2025). "However, also deciding what and how much to eat, as well as determining the appropriate insulin dosage, can be challenging when using alternative methods to deal with diabetes care." (PMID 40801339, 2025). "Diabetes mellitus, a common metabolic disorder, is characterized by persistently elevated blood glucose levels, which are typically the result of insufficient insulin production or inadequate response to insulin by the body." (PMID 39927165, 2025). "Given that family medicine residents (FMRs) often serve as primary care providers and play a critical role in managing diabetes care, it is imperative that they are aware of insulin overbasalization and actively combat such inertia to optimize treatment outcomes for their patients." (PMID 40909026, 2025). "These drugs primarily exert their glucose‐lowering effects by blocking the ATP‐sensitive potassium (KATP) channels on the membrane of pancreatic β cells, stimulating insulin secretion, thereby lowering blood glucose levels and controlling the progression of diabetes." (PMID 41357784, 2025). "Approximately 42% had medically treated diabetes, nearly half of whom received insulin." (PMID 40869571, 2025). "Diabetes is defined as a spectrum of metabolic disorders characterized by persistently elevated blood glucose levels due to inadequate insulin secretion, diminished insulin sensitivity, or both." (PMID 40566506, 2025). "This system faces challenges in delivering preventive and continuing diabetes care due to limitations in health workforce, and frequent shortages of surgical supplies and medications—including insulin, which contributes to poor glycemic control and diabetes complications." (PMID 40660469, 2025). "Overall, these findings suggest that compromised insulin delivery in obesity may play a role in the development of metabolic insulin resistance and diabetes." (PMID 40725728, 2025). "Interestingly, induction of diabetes per se also led to augmented alpha-cell de-differentiation, as well as transdifferentiation to insulin-positive beta-cells, likely as an inherent adaptive response to STZ induced beta-cell ablation." (PMID 40362452, 2025). "This suggests that TRPM3 could play a role in metabolic disorders such as diabetes, where impaired insulin secretion occurs." (PMID 40806522, 2025). "Therefore, if IDE’s function is compromised, excess insulin can accumulate in the bloodstream, worsening insulin resistance, disrupting glucose metabolism, and contributing to the progression of diabetes." (PMID 40724942, 2025).
diabetes (continued). "Critical priorities remain ensuring universal access to insulin, other essential medicines and diagnostics for glycaemia and blood pressure, as well as advocating for the routine inclusion of essential medications for diabetes." (PMID 41338627, 2025). "Hence, it is imperative to identify novel circulating proteins potentially involved in diabetes pathophysiology, particularly those controlling insulin secretion." (PMID 40270326, 2025). "The mediating effect of exogenous insulin on OA through diabetes and smoking was calculated." (PMID 41398760, 2025). "Whether SLC7 transporters directly modulate insulin granule biogenesis and exocytosis, and how their dysregulation contributes to beta cell dysfunction and failure in diabetes, are questions that have yet to be thoroughly explored." (PMID 40469683, 2025). "However, high insulin responses to glucose load have been observed in patient with diabetes (100~10,000 μU/mL), hepatic steatosis (200 μU/mL), and late pregnancy (300 μU/mL)." (PMID 40343778, 2025). "Notably, the DKA pattern, which includes previously diagnosed diabetes patients, was likely influenced by reduced access to insulin, continuous glucose monitoring sensors, and medical consultations during the pandemic outbreak." (PMID 40162434, 2025). "This study aimed to assess the impact of nine exercise interventions (resistance training [BT, ball training [BT], resistance + walking [RT+W alk], resistance + running [RT + Running], resistance + cycling [RT + bicycle], running, and Tai Chi) on insulin sensitivity in patients with diabetes." (PMID 40951419, 2025). "This approach provides valuable insights into insulin administration practices and enhances the understanding of how insulin management is approached by diverse patient groups, potentially informing more effective support strategies for individuals with diabetes." (PMID 40471961, 2025). "For example, in diabetes treatment, drug combinations can act simultaneously on different physiological pathways, which not only help to lower blood glucose levels, but also improve insulin sensitivity, thus achieving more comprehensive and effective control of diabetes mellitus." (PMID 39987494, 2025). "Furthermore, in addition to the impaired insulin functioning at the pancreas and ectopic fat accumulation at the liver, direct exposure to high levels of endogenous insulin at the pancreas and liver may increase the risk of pancreatic and liver cancers under diabetes condition." (PMID 40831756, 2025). "In addition, Fet A can induce apoptosis signals in pancreatic β-islet cells and then decrease insulin secretion and promote type 2 diabetes mellitus progression." (PMID 39790934, 2025). "PWCF who also have CF-related diabetes and are insulin-dependent may restrict insulin intentionally, which is classified as a diabetes-specific eating disorder (ED-DMT1), colloquially known as diabulimia." (PMID 41010297, 2025). "A previous study has suggested that a combination of insulin and other diabetes medications may reduce p-Tau levels." (PMID 41023469, 2025). "Diabetes, one of the most common metabolic diseases in humans, is a major public health problem, which is provoked by defects in insulin secretion due to pancreatic β-cell destruction (type 1) or by insulin resistance of peripheral tissues (type 2) (or by both)." (PMID 40161891, 2025). "For instance, a meta-analysis of 65 studies involving over 500,000 participants without diabetes reported that HOMA-IR was associated with a higher risk of coronary heart disease (HR = 1.46 per SD) compared to glucose (HR = 1.21) or insulin (HR = 1.04) alone." (PMID 41180178, 2025). "GLP1 analogs, TZDs, SGLT2 inhibitors, DPP4 inhibitors, SU and insulin show overall benefits for amyloid and tau pathologies, neuron health, inflammatory and vascular alterations, alongside improved cognition in animal models mimicking AD and/or diabetes." (PMID 41146261, 2025).
diabetes (continued). "Cognitive decline is a well-recognized complication of diabetes, hypothesized to be driven by glycemic fluctuations, insulin resistance, and disruptions in neuronal metabolism." (PMID 40004246, 2025). "Another limitation of the current study is that it does not address whether the proposed subcellular specialist zones coupling glucose sensing with insulin secretion are disrupted in diabetes." (PMID 39936989, 2025). "Moreover, HSPCs contribute to the regeneration of insulin-producing β-cells, leading to islet survival in diabetes studies." (PMID 40002238, 2025). "Accumulating evidence suggests that flavonoids may also play a role in glucose metabolism and insulin sensitivity, making them potential therapeutic agents for diabetes and its complications, including diabetic retinopathy." (PMID 40218965, 2025). "Thus, during development from normoglycemia to frank type 2 diabetes, insulin secretion follows a pattern of an inverted U: insulin concentrations initially rise, reach a peak at a certain moment, and then decrease when frank diabetes develops." (PMID 41009753, 2025). "Similarly, evidence in humans associates circadian misalignment with negative cardiometabolic outcomes in humans, including weight gain, impaired glucose tolerance, reduced insulin sensitivity, and diabetes." (PMID 39856244, 2025). "Liver fibrosis and cirrhosis induced by chronic HCV infection not only reduce the liver’s responsiveness to insulin but also accelerate the progression of diabetes through multiple mechanisms, including altered glycogen synthesis and storage, gluconeogenesis regulation, and insulin degradation." (PMID 41261617, 2025). "Diabetes mellitus is a chronic degenerative and multifactorial disease characterized by elevated glucose levels (hyperglycemia) due to impaired insulin secretion, decreased insulin action, or both, where type 1 and 2 diabetes are the most common." (PMID 40265815, 2025). "The results of this study suggest that quercetin may possess significant therapeutic potential when used in conjunction with other treatments for diabetes, through its direct action on β cells and the modulation of insulin secretion." (PMID 40807271, 2025). "Focusing on a specific subset of diabetic subjects, for example, only insulin-dependent subjects, might minimize the variability induced by diabetes and allow for a better examination of the mechanisms leading to plaque rupture." (PMID 41377472, 2025). "Managing insulin-treated diabetes requires significant resources and presents daily challenges." (PMID 41007688, 2025). "The observed sex difference in hazard ratios for “insulin only” relative to persons without diabetes is in line with previous studies showing that the excess mortality risk relative to persons without diabetes is stronger among women." (PMID 41350985, 2025). "Plants utilized for “hot” diabetes may exhibit anti-inflammatory effects that help protect pancreatic beta cells and enhance insulin function." (PMID 41311837, 2025). "It most commonly occurs in individuals with type 1 diabetes and is typically associated with the presence of diabetes-related autoantibodies, including glutamic acid decarboxylase antibody (GAD-Ab), insulinoma-associated protein 2 antibody (IA-2A), and insulin autoantibodies (IAA)." (PMID 41030450, 2025). "Moreover, an earlier report revealed reduced IL-9 levels in diabetes, and RNA sequencing data showed IL-9R expression in insulin target cells such as adipose tissue and the liver." (PMID 40962954, 2025). "Moreover, porcine insulin differs by only a single amino acid from that of human insulin, and it was administered to treat diabetes for nearly a century before the introduction of recombinant human insulin, making porcine islets an ideal source for ITx." (PMID 40243327, 2025).
diabetes (continued). "Propionic acid exerts beneficial effects on diabetes-related metabolic abnormalities through diverse mechanisms, including the enhancement of insulin sensitivity, regulation of glucose and lipid metabolism, attenuation of inflammation, and restoration of intestinal microbiota balance." (PMID 40860483, 2025). "However, evidence on CGM use that is generalizable to insulin-treated older adults with diabetes and ADRD remains limited." (PMID 41329488, 2025). "Elevated glucose levels and disrupted glucose metabolism in diabetes and Alzheimer’s disease(AD) may lead to insulin resistance, oxidative stress, and inflammation, affecting cognitive levels." (PMID 40171533, 2025). "We present a case of a 63-year-old female with type 2 diabetes mellitus (on metformin and insulin) who developed severe lactic acidosis, euglycemic diabetic ketoacidosis (DKA), and acute kidney injury (AKI) following a three-day history of gastrointestinal symptoms." (PMID 40400858, 2025). "Compared to CGL1, CGL2 patients have lower leptin levels, an earlier onset of diabetes, mild cognitive impairment (which may be related to increased seipin expression in the brain), higher insulin levels, and thus insulin resistance." (PMID 40508223, 2025). "Diabetes mellitus (DM) is a very common metabolic disease characterized by high glucose levels in the blood due to dysfunction in the pancreas to produce sufficient amounts of insulin hormone." (PMID 40747308, 2025). "Therefore, our objective for this systematic review is to compare the real-world effectiveness and safety of insulin biosimilars versus reference products in adults with types 1 and 2 diabetes mellitus." (PMID 40737300, 2025). "In addition, the measurement of fasting insulin and the calculation of HOMAIR and HOMAβ are essential for identifying subjects with diabetes requiring insulin therapy because of low insulin production, as seen in our population." (PMID 40284198, 2025). "Participants with longer duration of diabetes (>10 years) were found to have inadequate glycaemic control, which may be explained by the progressive nature of β-cell dysfunction and declining insulin secretion over time." (PMID 41395632, 2025). "While diabetes does increase dementia risk, its cognitive effects are generally mediated through metabolic dysfunctions—such as insulin resistance and chronic hyperglycemia—rather than direct vascular injury." (PMID 40565424, 2025). "For instance, 71.78% of participants (809 of 1,127) knew that the usual cause of diabetes is a lack of effective insulin in the body." (PMID 40352025, 2025). "We further assessed whether glycemic control, diabetes duration, and treatment (metformin and/or insulin) were related to specific molecular subtypes." (PMID 40764810, 2025). "Two treatment options are possible: start insulin as soon as cystic fibrosis diagnosis is made with the additional constraints of cystic fibrosis or wait while monitoring the patient’s clinical condition and start insulin when diabetes symptoms develop and therefore later." (PMID 39874570, 2025). "Specifically, the last point is of considerable importance in obesity because those affected mostly exhibit an impaired glucose metabolism or develop diabetes mellitus due to an insufficient effectiveness of insulin despite high serum concentrations, i.e., insulin resistance." (PMID 41470820, 2025). "However, we previously reported that chronic Cd exposure to LOAEL and NOAEL doses disrupts insulin signaling, lipid concentrations, and glucose homeostasis, leading to metabolic syndrome and diabetes in a time-dependent manner." (PMID 39103711, 2025). "One of the most central approaches to diabetes treatment is extracorporeal insulin infusion." (PMID 40465596, 2025). "Finally, comprehensive studies are needed to elucidate insulin’s effects on the cardiovascular system and kidneys, especially in the context of diabetes-related complications." (PMID 40725728, 2025).
diabetes (continued). "We assessed the prevalence of metabolic dysfunction‐associated steatotic liver disease (MASLD) and significant liver fibrosis in adults with type 1 diabetes mellitus (T1DM) and the association of MASLD with insulin sensitivity and continuous glucose monitoring metrics." (PMID 40083078, 2025). "The impact of diabetes on treatment, survival, and quality of life (QoL) is complex, with metformin treatment being associated with more prolonged RFS in EC patients, while insulin therapy has been linked to the risk of cancer deaths." (PMID 41440200, 2025). "These agents mimic GLP-1, enhancing glucose-dependent insulin secretion, suppressing glucagon release, and slowing gastric emptying to improve glycemic control, as indicated by reduced HbA1c level, a crucial measure in diabetes care." (PMID 40471297, 2025). "Additionally, basic research has demonstrated that mice with brain IR show impaired dopamine transport function, and MPTP-modeled mice show impaired insulin signaling in the substantia nigra, with diabetes and PD sharing common pathway damage." (PMID 40256390, 2025). "Diabetes mellitus (DM) remains one of the most prevalent and challenging chronic metabolic disorders worldwide, characterized by persistent hyperglycemia due to impaired insulin secretion, insulin resistance, or both [...]." (PMID 41304911, 2025). "Of all chronic diseases, the consequences of sudden loss of medical supplies are most serious for those with diabetes, with people living with type 1 diabetes being at risk of death within a few days without insulin." (PMID 40234304, 2025). "Diabetes predisposes individuals to HBV infection, likely due to a combination of impaired immune responses and repeated percutaneous exposures during routine diabetes management (glucose monitoring and insulin administration)." (PMID 41149058, 2025). "Additionally, albumin–drug conjugates have demonstrated promising outcomes in the treatment of chronic disease, such as albumin–insulin conjugates for diabetes management, by providing prolonged glucose control." (PMID 40699702, 2025). "Indeed, animal studies have demonstrated benefits in treating obesity and diabetes through AAV‐mediated expression of FGF21 or coexpression of insulin and glucokinase genes in skeletal muscles." (PMID 39949979, 2025). "Furthermore, less than one-third of the patients had knowledge about types of diabetes, the role of insulin in diabetes, insulin reaction, care of the wound, and the importance of tight elastic hoses or socks." (PMID 41401146, 2025). "Physical activity can improve insulin sensitivity, reduce neuroinflammation, and enhance cognitive function, suggesting that an active lifestyle may mitigate the impact of diabetes on cognition." (PMID 40296350, 2025). "Additionally, DigiBete allows users to store insulin ratios, dosage information, and pump settings, while also facilitating direct communication between patients and their diabetes care team." (PMID 40217595, 2025). "The non‐specialist (diabetes) will encounter issues surrounding insulin therapy in three areas." (PMID 40035222, 2025). "Lack of insulin secretion or inadequate insulin secretion causes type 1 diabetes mellitus, constituting 5%–10% of world diabetes instances." (PMID 40438603, 2025). "Targeting insulin resistance and insulin signaling: Targeting insulin resistance and signaling could yield neuroprotective benefits in diabetes-related cognitive impairment." (PMID 39822993, 2025). "By orally administering the vaccine combined with anti-CD3 antibodies to mice with acute and progressive onset of diabetes, we found that 63% of acute and 78% of progressive diabetic mice exhibited lower blood glucose levels, along with a remarkable increase in insulin positive cells after therapy." (PMID 40333284, 2025). "Consequently, the development of safer and more effective insulin replacement technologies or adjunctive therapies remains a pivotal research priority in diabetes management." (PMID 40647154, 2025).